ENO1 (enolase 1)
Diseases named in the same sentence as ENO1 in open-access papers (continued):
Sharing a sentence is not in itself a finding about the gene and the disease.
tumor (continued). "We observed a slight but not significant increase in HPD in tumor tissues compared to normal tissues, and the expression of ENO1 and TPI was significantly higher in tumor tissues than in normal ovarian tissues." (PMID 40491422, 2025). "Moreover, DNA vaccination targeting the overexpressed glycolytic enzyme alpha-enolase (ENO1), alone and much more in combination with CT or with MDSC inhibitor, efficiently delays tumor growth in vaccinated mice that spontaneously develop PDA." (PMID 39176093, 2024). "Moreover, the animal experiments further confirmed that KIAA1429 silencing diminished levels of YTHDF1, FOXM1, HK2, ENO1, and LDHA and suppressed tumor growth." (PMID 39060874, 2024). "In addition, HK2, ENO1, and LDHA mRNA levels were strikingly reduced in tumor tissues after KIAA1429 silencing (all P < 0.05)." (PMID 39060874, 2024). "Our qRT‐PCR experiments further revealed that METTL3 may promote the glycolysis capacity of ESCA cells by upregulating the expression of glycolysis‐related genes SLC2A1, GPI, PFKL, PGK1, ENO1 and PKM, thus facilitating tumour cell proliferation and migration." (PMID 38429907, 2024). "The study provided evidence that Hsp90 inhibition could block the marginal colocalization of Hsp90, ENO1, and PKM2 in tumor cells, moving colocalization closer to the perinuclear region and restoring their uniform distribution in the cytoplasm." (PMID 38874476, 2024). "While the extracellular tumor-linked roles of PGAM1, LDHA, PKM, TPI1, and PGK1 have not been tested, the anti-tumor actions of ALDOA 13, 18, ENO1 16, 18, and GAPDH 20 were reported." (PMID 37056934, 2023). "The α-Enolase (ENO1) specific Th17 cells have specific anticancer effects in PAAD patients, and compared with healthy mucosa, the abundance of Th17 in peripheral blood of tumor patients is low, while the proportion of FOXP3+Tregs is high." (PMID 37396042, 2023). "Our data showed that both ENO1, PFKFB3, NSDHL and SQLE have high expression levels in clinical HNSCC samples, and all of them presented higher expression in patient with recurrence tumor." (PMID 36841765, 2023). "In addition, the same trend was observed in the other four glycolysis enzyme markers, and we validate ENO1 and PGAM1 were overexpression in matched tumor part compared to normal side." (PMID 37065499, 2023). "Real-time qPCR analysis of glucose transporter and glycolytic genes in the xenograft tumor tissues showed that ACE2 overexpression suppressed the mRNA levels of SLC2A1, HK2, ENO1, PFKL, LDHA, and PDK1, while inhibition of Mas receptor with A779 restored the expression of glycolytic components." (PMID 37215979, 2023). "Together with the tumor-suppressing proteins such as CALR, ENO1, HSP, MSN, and UBC, which were enriched in tumor-suppressive CM, six recombinant proteins, such as HISTONE H4, PPIB, GJA1, CPE, S100A11, and PCOLCE, were identified as extracellular tumor-suppressing proteins." (PMID 36943734, 2023). "We cannot rule out the possibility of low ENO1 tumor expression in patients with high ENO1 aAb is a consequence of the immune-mediated elimination of high ENO1-expressing tumor cells, and selection of ENO1 negative, less antigenic tumor clones." (PMID 37910256, 2023). "In this study, we found that ENO1 knockout in PDAC cells affected the expression of abundant metabolism-related genes, confirming that the inhibition of ENO1 decreases proliferation and also suppresses tumor growth in vivo and in vitro." (PMID 36845730, 2023). "Although the direct functions of ENO1 in tumor cells have been extensively reported, paracrine ENO1 plays a critical role in the crosstalk between tumor cells and macrophages, which has not been clearly elucidated." (PMID 36614179, 2023). "Furthermore, we observed that ENO1, PFKFB3, NSDHL and SQLE were highly expressed in recurrent HNSCC tumor compared with first diagnosed HNSCC patients surviving at least 5 years." (PMID 36841765, 2023).
tumor (continued). "The glycolytic enzyme ENO1 is reported to be overexpressed in cancer and inflammatory cells and this promotes glycolysis, activates signalling pathways important in cancer including PI3K/AKT/mTOR, and drives tumor migration, invasion, and metastasis." (PMID 36564470, 2023). "LDHA and ENO1, two critical enzymes of glucose anaerobic oxidation, are succinylated and crotonylated by CPT1A and CBP, respectively, to upregulate the production of lactate, aggravating tumor development." (PMID 36577755, 2022). "Thus, the overexpression of ENO1 at the cell surface, where it functions as a surface-bound plasminogen receptor, contributes to the observed increase in metastatic capacity of PDAC tumour cells." (PMID 35204653, 2022). "Collectively these data imply that tumor resistance to doxorubicin mediated by MCL1 nuclear translocation can be overcome by treatment with small molecule inhibitors of Bcl-xL, A-1331852, but this mechanism is dependent upon ENO1." (PMID 35042842, 2022). "Taken together, these data suggest that circRHOBTB3 might regulate intracellular ROS levels to inhibit tumor cell proliferation and EMT by interacting with metabolic enzymes such as ENO1 and ENO2." (PMID 35148775, 2022). "Furthermore, ENO1-induced epithelial-to-mesenchymal transition (EMT), whereby epithelial cells are transformed into mesenchymal cells, also activates tumor metastasis." (PMID 35434271, 2022). "Although we clarified that circRHOBTB3 could inhibit CRC progression by repressing EMT and interacting with the metabolic enzymes ENO1 and ENO2, it is still a great challenge for us to target tumor-suppressive circRNAs for CRC therapy." (PMID 35148775, 2022). "In addition, we also identified significant up-regulation of Hyp on glycolysis enzymes pyruvate kinase (PKM), enolase (ENO1), and autophagy protein Parkin (PARK7) in tumor tissue." (PMID 36026437, 2022). "On considering studies of tumor drug resistance and related pathways, EMT may have a potential role in the regulation of ENO1 in drug-resistant CRC cells." (PMID 36620599, 2022). "ENO1, GCK, PGK1, and GAPDH are involved in tumor energy metabolism." (PMID 34194463, 2021). "It emerged from the present study that, in EC, local ENO1 protein upregulation was related only to tumor progression and not to overall survival." (PMID 33628097, 2021). "Analysis of the ENO1-specific peripheral and tumoral T cell receptor repertoire demonstrated that, in PDA patients, T cells could recirculate from the tumor to the periphery." (PMID 33804240, 2021). "It remained still a question whether the E2F3 transcription factor could play a role in the tumor formation and development of LUSC by binding to the ENO1 promoter, which required more sophisticated experiments for clarification." (PMID 34504528, 2021). "Importantly, Eno1 immunoprecipitated CD44, a cell-surface adhesion receptor, and its silencing suppressed Eno1-driven tumor inhibition." (PMID 34373756, 2021). "Obviously, the expression level of ENO1 was significantly different in the different tumor stages of CESC, LUAD, PICH, PAAD, and LIHC, but not in other types." (PMID 33643901, 2020). "Cancer datasets with incomplete information on overall survival (OS), tumor stage evaluation, or ENO1 expression, or without control samples were excluded from the analysis." (PMID 33643901, 2020). "The microRNA binding prevented the lncRNA’s interaction with its downstream target ENO1, which led to the reduction of ENO1 phosphorylation and suppression of the PI3K/AKT signaling, resulting in lower tumor cell proliferation and less aggressive cell behaviors." (PMID 32795333, 2020). "GRN, CD5L, ENO1, CHL1, CRISP3, VASN, and TNIK promote the invasive ability of tumor cells." (PMID 32953262, 2020).
tumor (continued). "Clinical data showed that ENO1 expression in metastatic lesions was higher than that in the primary lesions and that ENO1 upregulation was significantly correlated with the TNM stage and tumor differentiation grade, and predicted a poor prognosis in patients with HCC." (PMID 33184263, 2020). "Although, both MBP-1 and ENO-1 may bind to c-myc, only MBP-1 represses activity of this transcription factor and thus acts as a tumor suppressor." (PMID 31106201, 2019). "Although PI3K inhibitors down-regulate AKT activation and influence the regulation of downstream genes, included glycolytic enzymes as ENO1, this will not affect tumor cells." (PMID 29462900, 2018). "ENO1 can be discharged into the peripheral blood by necrosis and turnover of tumor cells or nonclassical secretory pathway such as exosome pathway." (PMID 29483925, 2018). "Notably, in three weeks after implantation, tumors from mice injected with sh-ENO1 Ishikawa cells appeared to display relatively lower expression levels of PI3K (P85α) and c-Myc in tumor tissues relative to the controls." (PMID 25951350, 2015). "In this study, a multiple approach was adopted to investigate the role of ENO1 in the invasion and metastasis of PDAC, and to develop possible therapeutic options, based on ENO1 regulation, aimed to counteracting the invasiveness of this tumor." (PMID 25860938, 2015). "Interestingly, Cappello and colleagues demonstrated that autologous DC, which were pulsed with recombinant ENO-1, increased T-cell proliferation and enhanced the production of interferon-γ (IFN-γ), a well-described anti-tumor agent." (PMID 25407528, 2014). "Either its function is not critical for tumor growth, or the remaining ENO1, or another activated compensatory pathway circumvents the loss of ENO2 protein." (PMID 24260413, 2013). "Because ENO1-specific Ab did not significantly influence tumor cell growth both in vitro and in vivo in our experimental setting, the effect of ENO1-specific Ab observed in this study is not likely due to Ab-mediated killing of tumor cells." (PMID 23894455, 2013). "Their role in tumor metastasis requires further investigation, but the role may be similar to that of proteins such as TPI-1, ENO1, and TAGLN2." (PMID 23504277, 2013). "Changes in ENO1 gene expression have been observed in several cancer cell models, whereas the clinical correlation of ENO1 expression to tumor status has not yet been clearly defined." (PMID 20886042, 2010). "The glycolytic genes, HK2, GAPDH and ENO1, were chosen as they mediate early, mid and final stages of glycolysis respectively, and all three ketolytic genes BDH1, OXCT1 and ACAT1 were analysed for MYCN amplification, survivability and tumour stage progression in three NB datasets." (PMID 41420301, 2025). "The differential interactome composition indicates a functional shift in EGFR signaling that may drive increased tumor cell adhesion (CD44, ITGB1, FN1), metabolic adaptation (GAPDH, ENO1) and stress response (HSPA4, HSP90AB1), consistent with mechanisms observed in therapy‐resistant CRC phenotypes." (PMID 41319168, 2025). "Rationally, targeting multiple nodes along the ENO1-ATP/lactate-AMPK/PI3K/AKT-mTOR axis may be effective for GC treatment, as indicated by the significant suppression of tumor growth by metformin (which inhibits ATP production) plus syrosingopine (which disrupts lactate homeostasis)." (PMID 41168198, 2025). "Additionally, ENO1 may mediate the PI3K/AKT pathway and its downstream signaling pathways to affect tumor cell activity." (PMID 39450258, 2024). "Moreover, RNA sequencing (RNA-seq) using tumor tissues from the Alb-Cre;S225Kfl/fl and S225Kfl/fl groups showed that SIX1 S225K knock-in regulated expression of many genes, including the glycolytic genes LDHA, ENO1, and PKM." (PMID 39617783, 2024).
tumor (continued). "Moreover, ongoing studies target the identified genes (ENO1, STMN1, PKM, CDK1), with therapies like enolase 1 depletion demonstrating efficacy across various tumor types by inhibiting glycolysis, growth, proliferation, migration, metastasis, and sensitizing tumors to chemotherapy and radiotherapy." (PMID 38840205, 2024). "However, the data obtained in PI3Kγ genetically-deficient mice showed superimposable effects on tumor microenvironment modification and anti-tumor effector immunity observed in TG100-115 treated mice, suggesting that the anti-tumor effects of ENO1 vaccination are mainly enhanced by PI3Kγ inhibition." (PMID 38824552, 2024). "Also, this study focused on the target proteins from cell-surface and secreted proteins, but other cytoplasmic or nuclear proteins, such as ENO1 and MSN, may act as extracellular tumor-suppressing proteins." (PMID 37894284, 2023). "Besides ENO1 and MSN, the engineered CM was enriched with polyadenylate-binding protein 1 (PABPC1) which also showed an opposing tumor-regulating role inside and outside tumor cells." (PMID 36923539, 2023). "Another study reported that the small molecule AP-III-a4 could directly bind to ENO1 and repress its catalytic activity, thereby prohibiting tumor cell survival without cytotoxicity to normal cells." (PMID 35836227, 2022). "Besides the effect of tumor cell-derived lactic acid, enhanced endogenous aerobic glycolysis, also known for induction of pro-tumoral TAMs, was confirmed by a proteomic analysis illustrating the upregulation of HK2, phosphofructokinase, and ENO1 in TAMs." (PMID 36358644, 2022). "The plasminogen receptors ENO1, histone H2B, Plg-RKT, ANXA2 and S100A10 have been shown to be expressed at the cell surface of human monocytes/macrophages, where they are involved in plasminogen activation and play an important role in the recruitment and migration of macrophages to tumour sites." (PMID 35204653, 2022). "Most notably, a significant proportion of the ENO1 protein redistributes to the surface of cancer cells, wherein it evolves proteolytic functions through activating the uPAR/plasminogen/MMP axis, thereby contributing to tumor progression in particular the process of metastasis." (PMID 34136381, 2021). "In addition to the recombinant Eno1 proteins, the partial silencing of CD44 in EO771 tumor cells reduced the inhibitory effect of recombinant Hsp90ab1 proteins on MTT-based viability, and partially suppressed the Hsp90ab1-driven downregulation of Lrp5, Runx2, and TGFβ in EO771 tumor cells." (PMID 34830748, 2021). "The findings show that ENO1 is not a predictor of overall survival, but that it is a predictor of tumor progression, suggesting that it may help to select patients with more aggressive disease who may benefit from targeted therapies." (PMID 33628097, 2021). "When EC cases were classified by degree of tumor differentiation, no statistically-significant difference in circulating ENO1 levels was found between grade 2 (n=11), grade 2/3 (n=7), and grade 3 tumors (n=14) (mean±SE pg/ml, 2143±178, 2161±384, 2225±326, respectively; p=0." (PMID 33628097, 2021). "No studies have reported that FOXM1 could bind to the ENO1 promoter to stimulate the proliferation of tumor cells." (PMID 34504528, 2021). "Notwithstanding these clinical correlations, it should be noted that the transcript analysis from tumor samples neither reflects the expression pattern of ENO1 in the small subpopulation of CSCs nor the amount of sENO1 protein present on the invadopodial surface." (PMID 34136381, 2021). "From two-dimensional electrophoresis (2-DE) protein analyses of human PDA tumor tissues, ENO1 resulted as being overexpressed compared to normal pancreatic tissues; however, in PDA cell lines cultured under growth factor stress, ENO1 was downregulated compared to parental cells." (PMID 33804240, 2021).
tumor (continued). "The study aimed to investigate the differential ENO1 protein expression in tumor and in adjacent non-cancerous tissue specimens, as well as in plasma from a series of primary EC, in BE patients and in matched healthy controls, in order to explore its clinicopathological relevance." (PMID 33628097, 2021). "Similarly, a DNA vaccine that targets enolase-1 (ENO1) in genetically engineered mice with PDAC showed promising results but did not completely eradicate tumor growth." (PMID 31540435, 2019). "Moreover, the study does not investigate whether ENO1 interacts with other immune cells to reshape the tumor immune microenvironment, potentially influencing the effectiveness of immunotherapy." (PMID 40665335, 2025). "However, the mechanisms involved in how ENO1 affects immune cell infiltration have not been fully elucidated, further in-depth investigation is required to be carried out to elucidate the exact function of ENO1 in the tumor-immune microenvironment." (PMID 35836227, 2022). "However, not all overexpression of ENO1 promoted tumor proliferation and inhibited apoptosis." (PMID 35434271, 2022). "However, direct evidence of the role of surface ENO1 in these processes in tumor cells is lacking." (PMID 23894455, 2013). "We found that ENO1 was overexpressed in bone marrow biopsies from both AML and MDS patients, and that this was not restricted to tumour cells." (PMID 38473245, 2024). "Western blotting data showed that the expression of ENO2, but not ENO1, was repressed by AP-III-a4 in tumor tissues, which was confirmed by IHC." (PMID 36588153, 2023). "In the cohort of resected patients, the Rho Spearman test showed a significant correlation between circulating aAb and upregulated expression in tumor tissue for FUBP1 (p = 0.0268), but not for ENO1 (p = 0.3172)." (PMID 37910256, 2023). "The findings imply that LTF, AZU1, and ENO1 are related to tumor grade, while LCP1 is not substantially different among tumor stages." (PMID 37304069, 2023). "For instance, the expression level of CD44, which may interact with Eno1 and MSN, can be expressed higher in cancer cells than noncancer cells, and thus the impact of CD44-mediated cytotoxicity is stronger in tumor cells." (PMID 36810561, 2023). "ENO1 was found to be overexpressed on the surface of human PDAC cells at intermediate or high levels in metastatic cell lines and was absent or present at low levels in primary tumour-derived cell lines." (PMID 35204653, 2022). "Although promising, the ENO1 DNA vaccine does not completely eradicate the tumor, which, after an initial growth inhibition, returns to proliferate again, especially when Tregs and MDSC ensue in the tumor mass." (PMID 29462900, 2018). "However, the primary limitation of this study is that it focuses mainly on the impact of ENO1 on the function and polarization of CD8+ T cells and macrophages within the tumor microenvironment, without exploring the broader molecular mechanisms through which ENO1 regulates these immune cells." (PMID 40665335, 2025). "We found that stem cell-like GBM tumor subpopulations possessed higher basal levels of glycolytic activity and increased expression of several glycolysis-related enzymes including, GLUT1/SLC2A1, PFKP, ALDOA, GAPDH, ENO1, PKM2, and LDH, compared to their non-stem-like counterparts." (PMID 37420311, 2023). "ENO1 and RAC1 also showed high levels of expression in EGFR mutant LUADs aligning with previous studies demonstrating that ENO1 expression is greater in LUAD tumor samples relative to non-cancerous tissue, and the RAC1 splice variant RAC1B enhances LUAD tumor formation in vivo." (PMID 38260835, 2023). "Notably, among the eight cell lines tested, ENO1 was expressed at intermediate or high levels in metastatic cell lines (Hs766T, T3M4, CFPAC-1, L3.6pl), and was absent or expressed at lower levels in primary tumor-derived cell lines (BxPC3, PANC-1, PT45, Mia-PaCa2)." (PMID 25860938, 2015).